HERPUD2 (HERPUD family member 2)
Description:
Could be involved in the unfolded protein response (UPR) pathway.
Synonyms: FLJ22313
Tractability: Antibody: UniProt predicts a signal peptide or a membrane-spanning region. PROTAC: ubiquitination databases record sites on it.
Gene: Protein-coding gene on chromosome 7 (35,632,659 to 35,697,459, reverse strand). Ensembl gene ENSG00000122557.
Subcellular location: Membrane
Subcellular location (Human Protein Atlas): Nucleoli; Nucleoli rim
Gene Ontology:
Molecular function: protein binding
Biological process: endoplasmic reticulum unfolded protein response; spermatogenesis
Cellular component: membrane
Genetic constraint (gnomAD): Loss-of-function variants: 10 observed, 37.57 expected, observed/expected ratio (o/e) 0.27, 90% interval 0.16 to 0.45. The upper end of that interval is the gene's LOEUF score, 0.45, which puts it in group 2 of 6, group 1 being the genes least tolerant of losing a copy. Missense variants: 350 observed, 402.77 expected, observed/expected ratio (o/e) 0.87, 90% interval 0.8 to 0.95. Synonymous variants: 137 observed, 141.45 expected, observed/expected ratio (o/e) 0.97, 90% interval 0.84 to 1.12.
Homologues: Orthologues: chimpanzee HERPUD2 (99% identical), macaque HERPUD2 (98% identical), dog HERPUD2 (95% identical), pig HERPUD2 (94% identical), rabbit HERPUD2 (92% identical), mouse Herpud2 (89% identical), rat Herpud2 (89% identical), guinea pig HERPUD2 (74% identical), tropical clawed frog herpud2 (60% identical), zebrafish herpud2 (55% identical), Drosophila melanogaster Herp (28% identical), Caenorhabditis elegans tag-353 (23% identical). Paralogues in human: HERPUD1 (38% identical).